CRP (C-reactive protein)
Diseases named in the same sentence as CRP in open-access papers (continued):
Sharing a sentence is not in itself a finding about the gene and the disease.
appendicitis (continued). "Previous studies have identified certain factors that could be indicative of complicated appendicitis, including age younger than 5 years, experiencing symptoms for more than 24 h, having a white blood cell count (WBC) greater than 12 × 109, and a C-reactive protein (CRP) level greater than 10 mg/L." (PMID 37817011, 2023). "Conversely, WCC and CRP showed higher sensitivity in detecting non-perforated appendicitis." (PMID 37929270, 2023). "The specificities of WCC for non-perforated appendicitis was 42.86% and that for CRP was 60.00%." (PMID 37929270, 2023). "The sensitivity of WCC for non-perforated appendicitis was 73.28%, whereas that for CRP was 76.53%." (PMID 37929270, 2023). "Furthermore, in their study, hyperbilirubinemia demonstrated a PPV of 91% and CRP showed a specificity of 71% for acute non-perforated appendicitis." (PMID 37929270, 2023). "Bilirubin vs. WCC vs. CRP for perforated appendicitis vs. non-appendicitis." (PMID 37929270, 2023). "Bilirubin vs. WBC vs. CRP for non-perforated appendicitis vs. normal appendices." (PMID 37929270, 2023). "Besides, it demonstrated a positive predictive value of 58.1% and a negative predictive value of 85.1%, so there is a probability that about 85% of patients with a CRP value of less than 63.3 mg/L will not actually have a complicated acute appendicitis." (PMID 35106154, 2022). "TLC has a sensitivity of 85%, specificity of 75%, positive predictive value of 44% and negative predictive value of 100% in predicting acute appendicitis while CRP has a sensitivity of 93.3%, specificity of 86.6 positive predictive value of 55% and negative predictive value of 88%." (PMID 35495380, 2022). "Adding a CRP test may therefore improve decision-making for GPs who adopt both high (to avoid negative referrals) and lower (to avoid missing appendicitis) referral thresholds." (PMID 35535699, 2022). "Indeed, a CRP test in children with acute abdominal pain but no signs or symptoms of appendicitis is meaningless." (PMID 35535699, 2022). "Another study concluded that increased CRP is not a definite indicator of acute appendicitis." (PMID 35495380, 2022). "When comparing these markers with individual histopathological presentations, CRP was found more predictive of complicated (P < 0.001) and perforated appendicitis (P < 0.001) when compared with simple, non-perforated and suppurative appendicitis." (PMID 35495380, 2022). "There are multiple new studies looking at other inflammatory markers to help diagnose acute appendicitis; for example, the study by Bozlu looked at the red blood cell distribution width in combination with WBC and CRP with no clear role in ruling out appendicitis." (PMID 36514558, 2022). "It has been suggested by additional studies that in order to strengthen their sensitivity and specificity, hyponatremia should be considered concurrently with WBC and CRP to achieve the most accurate outcome in terms of differentiating complicated appendicitis from non-complicated appendicitis." (PMID 35884054, 2022). "Several studies suggest that normal levels of WBC and CRP rule out appendicitis." (PMID 33907858, 2021). "In this study, we developed two scoring systems by including variables, namely the CRP level, CT features (three grades of FS and appendicolith), and ascites (model 1) or NLR > 10 (model 2), to distinguish between complicated and uncomplicated acute appendicitis." (PMID 34645500, 2021). "However, a significant difference was found for CRP (controls 13.60 (16.83) vs. appendicitis 60.20 (33.23) mg/dl, p = 0.023), but not for white blood count (controls 9.22 (5.86) vs. appendicitis 13.04 (3.00) × 109/l, p = 0.23)." (PMID 33106536, 2020). "WBC, percentage of neutrophils and CRP could predict non-gangrenous appendicitis with specificity of 0.866 (sensitivity 0.268), 0.941 (sensitivity 0.237) and 0.897 (sensitivity 0.340), respectively." (PMID 33060696, 2020).
appendicitis (continued). "The results of multivariate logistic regression analysis showed that only CRP (t = −3.475, P = 0.002) and sB7H3 (t = −2.309, P = 0.023) were statistically different between the nonperforated appendicitis group and the perforated appendicitis group." (PMID 32953890, 2020). "Furthermore, there were significant differences in the levels of CRP and sB7H3 between the nonperforated appendicitis group and the perforated appendicitis group, in which the values of AUROC were 0.734 and 0.675, respectively." (PMID 32953890, 2020). "In a series of 83 consecutive elderly patients operated on for a clinical suspicion of acute appendicitis, although elevated leukocyte count and CRP value cannot effectively establish the diagnosis of acute appendicitis, unelevated values excluded it with a 100% negative predictive value." (PMID 32156296, 2020). "Additionally, only the levels of CRP and sB7H3 were statistically different between the nonperforated appendicitis group and the perforated appendicitis group." (PMID 32953890, 2020). "However, duration of symptoms, WBC count, CRP, neutrophils percentage, and serum sodium level did not increase the odds of a perforated diagnosis of acute appendicitis despite their values were significantly different between groups." (PMID 31641539, 2019). "General inflammation markers such as WBC count, levels of CRP and procalcitonin failed to distinguish specific etiology of acute surgical abdomen ranging from relatively benign conditions, such as acute appendicitis, to more sever ailments, such as colon perforation." (PMID 30322074, 2018). "The score with following parameters, PAS ≤ 5, CRP < 5 mg/L, and a negative US, could almost rule out appendicitis." (PMID 28044133, 2016). "Therefore, this clinical score, combining PAS, CRP, and US, seems useful and easily applicable to safely rule out appendicitis for a substantial part of children seeking the pediatric ED with abdominal pain." (PMID 28044133, 2016). "However, CRP is not specific for appendicitis, and one should consider the presence of other diseases such as a diverticulum, inflammation of the ileum, or urogenital and gynecological disorders." (PMID 19878592, 2009). "CRP and WBC values may be normal in 8 % of infants with proven appendicitis." (PMID 17132173, 2006). "Identification of children with severe appendicitis was supported by IL-6 or CRP but not WBC." (PMID 17132173, 2006). "Low lymphocyte count and high CRP/Albumin ratio combined into a predictive model may have a role in the selection of patients who deserve appendicectomy instead of non-operative management of acute appendicitis." (PMID 36707812, 2023). "In addition, other risk factors could also be identified—most of them were again indicator of severe appendicitis: age, preoperative laboratories (CRP, WBC count and hemoglobin) as well as conversions rate, duration of surgery and presence of an intraoperative complicated appendicitis." (PMID 36708422, 2023). "However, CRP may not be a useful marker of clinical healing in acute appendicitis patients who are discharged early." (PMID 36225527, 2022). "However, CRP and procalcitonin, as well as novel derived biomarkers such as neutrophil-to-lymphocyte ratio (NLR), platelet-to-lymphocyte ratio (PLR), and monocyte-to-lymphocyte ratio (MLR) were successfully used as severity markers in predicting complicated appendicitis in children." (PMID 36676645, 2022). "Some studies have demonstrated that CRP is more sensitive in determining the existence of perforated appendicitis, while the elevated white blood cell count is more sensitive in deciding whether a patient has or does not have acute appendicitis." (PMID 34828754, 2021). "In our study, the rates we found for WBC, CRP, and NC were slightly lower than those found in the literature regarding specificity values, but they generally agree with the literature, and, as in other studies, we cannot rule out acute appendicitis from the rates in our study." (PMID 31183274, 2019).
appendicitis (continued). "However, no report has evaluated the role of CRP for surgical indication of appendicitis." (PMID 19878592, 2009). "Furthermore, a criterion for discrimination between phlegmonous and perforated appendicitis could be found not for leukocytes, but for IL-6 and mostly impressive for CRP." (PMID 17132173, 2006). "Among the 35 patients without acute appendicitis, 4 (11.4%) had positive CRP/MAS and 31 (88.57%) had negative CRP/MAS." (PMID 39677268, 2024). "Among the 195 patients with acute appendicitis 178 (91.3%) had positive CRP/MAS and 17 (87.17%) had negative CRP/MAS." (PMID 39677268, 2024). "Conversely among the 182 patients with positive CRP/MAS; 178 (97.8%) had acute appendicitis and 4 (2.2%) had normal appendix." (PMID 39677268, 2024). "Among the 48 patients with negative CRP/MAS; 17 (35.4%) had acute appendicitis and 31 (64.3%) had normal appendix." (PMID 39677268, 2024). "In this study, univariate analysis showed that body temperature, CRP, WBC, NE, and bilirubin were significantly higher in patients with non-simple appendicitis." (PMID 38253872, 2024). "Among the 182 patients with positive CRP/MAS; 178 (97.8%) had acute appendicitis and 4 (2.2%) had normal appendix." (PMID 39677268, 2024). "The data collected showed that in 53 cases (100%) where the US was negative for appendicitis, WCC, neutrophil, and CRP were within normal range." (PMID 39640104, 2024). "Median levels of the WCC, CRP and NLR (but not the CFP) were increased in the complicated appendicitis cohort when compared with the normal cohort." (PMID 37093074, 2023). "It does not include C - reactive protein (CRP) as a variable, despite several studies demonstrating the usefulness of CRP in evaluating patients with acute appendicitis." (PMID 36711320, 2023). "Bilirubin had higher specificity (94.29%) for detecting non-perforated appendicitis than normal appendices (odds ratio = 3.88), while WCC and CRP showed higher sensitivities." (PMID 37929270, 2023). "In a pooled analysis of 31 143 children attending hospital with symptoms of appendicitis the most sensitive single blood tests for discriminating appendicitis from non-surgical conditions were WCC or ANC, and combining WCC with CRP increases this further." (PMID 36328382, 2022). "Our findings suggest that at our center, hyponatremia is a greater significant predictive factor than inflammatory markers (CRP, WCC, and neutrophil count) for complicated appendicitis in adults but not in our pediatric cohort." (PMID 35949749, 2022). "Unlike previously reported scores, this one includes C-reactive protein (CRP), which has been previously reported to have high power in discriminating between simple and advanced acute appendicitis." (PMID 33921577, 2021). "Since appendicitis has a broad spectrum of clinical presentation, we then integrated five predictors (vomiting, RLQ pain, negative stool OB, higher CRP level, and higher WBC level) into a revised combined model." (PMID 33050667, 2020). "Only the levels of CRP, FIB, and sB7H3 had a remarkable rising trend in AA-based groups, while differences in the levels of CRP and FIB between simple appendicitis and purulent appendicitis were not statistically significant." (PMID 32953890, 2020). "Previous publications have stated a 100% negative predictive value for acute appendicitis, if both WBC and CRP are normal, whereas other reports found appendicitis in the presence of normal CRP, WBC, and neutrophils." (PMID 33313029, 2020). "White blood cell count with C-reactive protein and neutrophils percentage with CRP are important markers in distinguishing perforated appendicitis from nonperforated appendicitis in pediatric subjects." (PMID 31641539, 2019). "Plasma levels of IL-6, CRP, MCP-1, PCT, and SAA were significantly different (p < 0.001) in children with appendicitis compared to those with nonappendicitis abdominal pain." (PMID 30918467, 2019).
appendicitis (continued). "There was a strong negative correlation between serum FA levels and CRP and WBC levels in the acute appendicitis group." (PMID 31547519, 2019). "It seems that suspicion of appendicitis can be ruled out in a substantial number of patients when US is integrated with PAS and CRP." (PMID 28044133, 2016). "A second end point is to investigate and compare the kinetics of CRP after IC resection in CD patients against two control groups of ‘non-IBD’ surgical patients, such as acute appendicitis and right colon cancer." (PMID 27551522, 2016). "However, in the classification of appendicitis subgroups, the relationship between CRP and LOS was significant in simple appendicitis, but not significant in gangrenous appendicitis and perforated appendicitis." (PMID 39726534, 2024). "Other biochemical markers such as CRP, calcitonin, and calprotectin, as well as the APPY1 biomarker panel which combines CRP, WCC, and myeloid reactive protein level, can be used to rule out or diagnose appendicitis." (PMID 39640104, 2024). "Of the remaining 68 patients in which appendicitis was ruled out, 45 patients (59%) had a diagnosis at discharge recorded as "non-specific abdominal pain" with all three inflammatory marker tests (WCC, neutrophils, and CRP) within normal limits." (PMID 39640104, 2024). "Additionally, we explored the link between hyperbilirubinemia and perforated appendicitis and compared the specificity of bilirubin with WCC and CRP levels for diagnosing both non-perforated and perforated appendicitis." (PMID 37929270, 2023). "Sixty-seven included studies consisted of 34 839 children (13 342 with appendicitis and 21 497 without) which evaluated the following tests: WCC, CRP, ANC, neutrophils as percentage of leucocytes, procalcitonin, combined WCC and CRP, and combined WCC/CRP/neutrophil percentage." (PMID 36328382, 2022). "However, the use of CRP alone or WBC count in combination with CRP helps to differentiate between PA and non-perforated appendicitis (Grönroos, 2001)." (PMID 35431963, 2022). "However, in some cases, none of the new inflammatory markers, including leukocyte, C-reactive protein (CRP), or PCT, can identify acute appendicitis with high specificity and sensitivity." (PMID 34828754, 2021). "Analyses on the entire cohort showed the ability to predict uncomplicated and non-gangrenous appendicitis using CRP, WBC or percentage of neutrophils with high specificity, indicating that low values could be of use as markers for less severe appendicitis." (PMID 33060696, 2020). "The sensitivity of combining both WBC counts and CRP levels was extremely high in children with acute appendicitis, while WBC counts or CRP alone did not aid in the diagnosis because normal values of both WBC and CRP were very rare in pediatric acute appendicitis." (PMID 33050667, 2020). "Furthermore, significant variations existed between the perforated and non-perforated appendicitis groups in terms of WBC counts, neutrophils ratio, lymphocytes ratio, CRP, procalcitonin, total bilirubin, direct bilirubin, albumin, prealbumin, and other laboratory test results (p < 0.05)." (PMID 38509094, 2024). "A decision tree incorporating the proteins CRP, ferritin, SAA, regulated on activation normal T-cell expressed and secreted (RANTES), monokine induced by gamma interferon (MIG), and PCT demonstrated excellent specificity (0.920) and negative predictive value (0.882) for children with appendicitis." (PMID 30918467, 2019).
colorectal cancer (309 papers, 2002 to 2026). A primary or metastatic malignant neoplasm that affects the colon or rectum. "We have previously shown that elevated CRP levels were linked to poorer colorectal cancer prognosis." (PMID 40985344, 2025). "A higher CRP response following surgery is associated with an increased risk of cancer recurrence, all-cause mortality, and time-to-recurrence in patients with colorectal cancer." (PMID 40383853, 2025). "This meta-analysis demonstrated that peritoneal fluid CRP is a promising biomarker for detecting AL after colorectal cancer surgery, exhibiting moderate to high diagnostic accuracy." (PMID 40142907, 2025). "Elevated CRP levels, which are associated with cachexia development in various cancer types, were only found to be increased in patients with colorectal cancer with liver metastases." (PMID 41221702, 2025). "A retrospective cohort study including 298 patients undergoing RAS or LAS for colorectal cancer in a planned setting indicated that LAS was associated with a significantly increased CRP response in the early postoperative course." (PMID 40383853, 2025). "Subsequently, Another meta-analysis conducted two years subsequent refuted any association between circulating CRP levels and the risk of colorectal cancer CRC." (PMID 39980561, 2025). "In contrast, a decreasing CRP trajectory pattern was associated with a reduced risk of esophageal and colorectal cancer." (PMID 41409302, 2025). "CRP, a marker of systemic inflammation, has been linked to poorer surgical outcomes in colorectal cancer." (PMID 39851480, 2025). "Chronic inflammation is closely linked to advanced stages of colorectal cancer and metastasis, being associated with elevated inflammatory markers such as C-reactive protein (CRP) and IL-6." (PMID 39682667, 2024). "Specifically, the preoperative C-reactive protein/albumin ratio was independently associated with long-term prognosis in patients aged ≥ 70 years with stage I-III colorectal cancer after curative resection." (PMID 38280961, 2024). "CRP, a marker of systemic inflammation, has consistently been linked to poor survival outcomes in colorectal cancer." (PMID 39001534, 2024). "Regarding the breakdown of complications, it has been reported that high postoperative CRP in gastric cancer, esophageal cancer, and colorectal cancer is associated with an increased risk of anastomotic leakage." (PMID 38398224, 2024). "C reactive protein (CRP), which is a good indicator of inflammation, has been found to be associated with prognosis in cervical cancer as well as in colorectal cancer and esophageal cancer." (PMID 38783223, 2024). "A higher risk of developing colorectal cancer is linked to high levels of circulating C-reactive protein (CRP) and erythrocyte sedimentation rate (ESR)." (PMID 38107701, 2023). "Emerging evidence indicates that some patients with colorectal cancer will have a systemic inflammatory consumption reaction, manifested by increased C-reactive protein (CRP) and decreased albumin, thus causing chronic inflammatory anemia." (PMID 38144195, 2023). "We found that the anti-TNF effect was associated with an absolute risk reduction in the risk of colorectal cancer (-2.1%, 95%CI -3.8% to -0.4%, p = 0.01) per 1 mg/L reduction in serum C-reactive protein." (PMID 36618924, 2022). "We performed colocalization analysis for CRP levels and colorectal cancer within ±15 kilobase pairs of the TNRSF1A gene that encodes TNFR1 protein." (PMID 36618924, 2022). "In harmonizing the SNPs-CRP association estimates and the SNPs-colorectal cancer estimates, we excluded the SNP rs4149569 for being palindromic with intermediate allele frequencies." (PMID 36618924, 2022). "We quantified the mediating roles of C‐reactive protein (CRP), leptin, fasting insulin, and estradiol in the effect of adiposity on estrogen receptor (ER)‐positive breast, endometrial, and colorectal cancer risk in postmenopausal women." (PMID 35048536, 2022).